ZNF724 (zinc finger protein 724)
Description:
May be involved in transcriptional regulation.
Synonyms: ZNF724P
Tractability: PROTAC: ubiquitination databases record sites on it.
Gene: Protein-coding gene on chromosome 19 (23,221,599 to 23,250,394, reverse strand). Ensembl gene ENSG00000196081.
Subcellular location: Nucleus
Pathways (Reactome):
Gene expression (Transcription): Generic Transcription Pathway
Gene Ontology:
Molecular function: DNA-binding transcription factor activity, RNA polymerase II-specific; RNA polymerase II cis-regulatory region sequence-specific DNA binding
Biological process: regulation of DNA-templated transcription; negative regulation of transcription by RNA polymerase II
Cellular component: nucleus
Genetic constraint (gnomAD): Loss-of-function variants: 3 observed, 9.01 expected, observed/expected ratio (o/e) 0.33, 90% interval 0.15 to 0.86. That is too few expected variants to judge how well the gene tolerates losing a copy. Missense variants: 151 observed, 159.33 expected, observed/expected ratio (o/e) 0.95, 90% interval 0.83 to 1.09. Synonymous variants: 52 observed, 50.9 expected, observed/expected ratio (o/e) 1.02, 90% interval 0.82 to 1.29.
Homologues: Orthologues: mouse Zfp738 (53% identical), mouse Zfp595 (51% identical), mouse Zfp457 (50% identical), rat AABR07009105.1 (38% identical), mouse Zfp953 (27% identical). Paralogues in human: ZNF681 (74% identical), ZNF43 (73% identical), ZNF85 (72% identical), ZNF254 (71% identical), ZNF708 (70% identical), ZNF726 (70% identical), ZNF429 (69% identical), ZNF728 (68% identical), ZNF93 (66% identical), ZNF493 (63% identical), ZNF676 (63% identical), ZNF492 (58% identical), and 164 more.
Diseases named in the same sentence as ZNF724 in open-access papers:
ZNF724 is named in the same sentence as 4 diseases in open-access papers, as found by Europe PMC text mining. Sharing a sentence is not in itself a finding about the gene and the disease. The quoted sentences say what the papers report.
gout (3 papers, 2019 to 2024). A condition characterized by painful swelling of the joints, which is caused by deposition of urate crystals. "Another GWAS study showed that three loci (CNTN5, MIR302F and ZNF724) were related to the mechanism of gout development, which is different from the gout risk loci that raise serum uric acid levels we know now." (PMID 35909538, 2022). "After Bonferroni correction (p<2.5×10–2=0.05/2), rs12980365 of ZNF724 showed a significant association with gout in persons of European ancestry (p=8.54 × 10–3)." (PMID 31289104, 2019). "Interestingly, the present study also demonstrated that rs12980365 of ZNF724 showed a significant association with gout in persons of European ancestry within GUGC, which compared gout and non-gout individuals." (PMID 31289104, 2019). "In addition, three genes (CNTN5, MIR302F, and ZNF724) were detected as ‘gout vs. asymptomatic hyperuricemia’-specific genetic factors." (PMID 38397902, 2024). "We also identified rs12980365, an SNP of ZNF724, as a potential gout locus." (PMID 31289104, 2019). "This new approach enabled us to identify two novel gout loci (rs7927466 of CNTN5 and rs9952962 of MIR302F) and one suggestive locus (rs12980365 of ZNF724) at the genome-wide significance level (p<5.0×10–8)." (PMID 31289104, 2019).
ZNF724 also shares sentences with these, for which no sentence is quoted: cancer (1 paper); glioma (1); hyperuricemia (1).